ENSG00000276670
Gene: Miscellaneous RNA gene on chromosome 2 (44,940,045 to 44,940,245, forward strand). Ensembl gene ENSG00000276670.
Gene Ontology:
Biological process: regulation of gene expression